NLGN1 (neuroligin 1)
Diseases named in the same sentence as NLGN1 in open-access papers (continued):
Sharing a sentence is not in itself a finding about the gene and the disease.
tumor (8 papers, 2021 to 2025). "Finally, NLGN1 promotes cell migration, a mesenchymal trait which is also linked to tumor budding, in HuTu 80 and HCT116 cells." (PMID 36056393, 2022). "The transmembrane protein Neuroligin 1 (NLGN1) is reported to interact at the synapse with the tumor suppressor Adenomatous Polyposis Coli (APC), which is intensively involved in the pathogenesis of CRC and is a key player in the WNT/β-catenin pathway." (PMID 37483484, 2023). "The analysis on TMA showed that NLGN1 was expressed by tumor cells as follow: about half of the TMA’s cores (75, 52%) were positive for NLGN1: 5 with score 3 (3,3%), 21 with score 2 (14%) and 49 with score 1 (32,7%)." (PMID 36056393, 2022). "Because of the established role of the neurotrophic factor glial cell line-derived neurotrophic factor (GDNF) in tumor–nerve interactions, we assessed a potential NLGN1–GDNF cooperation." (PMID 35053395, 2022). "Globally, the only consistent effect of NLGN1 on tumor cells was to stimulate their ability to cross the endothelial barrier in all cell lines used." (PMID 36056393, 2022). "Certainly, studies on larger cohorts are needed to validate NLGN1 as a routine marker of tumor budding/EMT and lymphovascular invasion." (PMID 36056393, 2022). "Our work is the first to demonstrate that NLGN1 immunohistochemical expression is sustained in high grade tumor budding single cells and in lymphovascular emboli." (PMID 36056393, 2022). "We next focused on the possibility that NLGN1 was expressed by the most infiltrative tumor cells by analyzing the invasive front of the tumor (tumor cell budding) and tumor emboli." (PMID 36056393, 2022). "Before this report, we demonstrated that NLGN1 is expressed by prostatic and pancreatic cancer tissues in distinct stages and tumor districts using immunohistochemistry on human tissue microarrays." (PMID 36499024, 2022). "Primary tumor growth, as well as metastatization to liver and lungs, was unaffected in all cases by NLGN1, indicating a site-specific activity in the metastatic promotion." (PMID 36056393, 2022). "We also observed some additional putative regulatory interactions in Gleason pattern 4 tumours around the NLGN1 and CDH9 loci, even though the increase in the number of links were not as high as around the NRXN1 locus." (PMID 34911933, 2021). "In the MMRd subtype, non-inflamed phenotypes exhibited upregulation of CD99 and NLGN1, both of which have been implicated in immune suppression and tumor progression." (PMID 39751650, 2025). "The overall analysis showed that NLGN1 positive tumors showed systematically strong staining in high grade tumor budding single cells and lymphovascular emboli, proving our initial hypothesis." (PMID 36056393, 2022). "EMT is also directly linked to tumor budding and the NLGN1-induced EMT phenotype could explain our observation of NLGN1-stained budding cells in human samples." (PMID 36056393, 2022). "Notably, genomic regions associated with the neuronal adhesion genes, NRXN1, NLGN1 and CDH9, are highly accessible in Gleason pattern 4 vs. 3 tumours." (PMID 34911933, 2021). "Prompted by the presence of NLGN1-positive cells in tumor emboli and given that crossing the endothelial monolayer is a crucial event for both intravasation and extravasation during metastatization, we evaluated the ability of NLGN1 to promote the process of trans-endothelial migration (TEM)." (PMID 36056393, 2022). "When exploring the intracellular pathways on which NLGN1 could impact, we first considered that the tumor suppressor APC is required for localizing NLGN1 to neuronal nicotinic synapses, implicating a functional interaction at the cell membrane of both proteins." (PMID 36056393, 2022). "It was thus possible to identify genes (CNTN1, FAT3, EPHA3, EPHA5, NLGN1, etc.)that contribute to PC2 and are differentially expressed in radial glial cells between normal and tumor samples." (PMID 38609519, 2024).
tumor (continued). "We investigated a potential cooperation between NLGN1 and the neurotrophic factor glial cell line derived neurotrophic factor (GDNF) because this factor is known to play a function in tumor–nerve interactions." (PMID 36499024, 2022). "To validate our results that show a significant enrichment in the chromatin accessibility profiles of high-grade tumours for neuronal adhesion molecules NRXN1, NLGN1 and CDH9, we analyzed the bulk ATAC-seq profiles using the TCGA PRAD data set35." (PMID 34911933, 2021). "However, NLGN1 could also promote intravasation, as it is expressed by single cells in high-grade tumor budding and intravasated emboli and it may promote EMT (a necessary step for primary tumor spread and intravasation), as seen by β-cat nuclear translocation and gene expression modulation." (PMID 36056393, 2022).
psychiatric disorder (7 papers, 2015 to 2025). A disorder characterized by behavioral and/or psychological abnormalities, often accompanied by physical symptoms. "Although not segregating closely with BD, we identified CNVs affecting intronic regions of candidate genes previously implicated in psychiatric disorders (i.e., NLGN1, CNTNAP2, KCNB2 and CNTN5), each in different families." (PMID 29531218, 2018). "NLGN1 has been associated with a variety of psychiatric disorders and may be directly related to synaptic function and synaptic plasticity." (PMID 27219346, 2016). "Additionally, the NLGN1 gene is also found to be linked with PTSD and other psychiatric disorders." (PMID 34639084, 2021).
neurological disorders (5 papers, 2018 to 2023). "Both NLGN1 and NEGR1 are involved in mammalian nerve development, and they may induce neurological diseases." (PMID 33391332, 2020).
infection (3 papers, 2012 to 2022). The state of being infected such as from the introduction of a foreign agent such as serum, vaccine, antigenic substance or organism. "Thus we first examined dendritic spine densities in newborn granule cells 21 days after infection with the HA-neuroligin-1 IRES GFP retrovirus." (PMID 23110172, 2012). "While the extent and magnitude of gene expression changes were not as robust as the virulent ZIKV-MR766 infection model, we nevertheless saw significant changes in the expression of 7 of 14 genes analyzed, including Adora2, Cacna1e, Ccl5, Gpr84, Nlgn1, Pmch, and Tor3a." (PMID 35462541, 2022).
neurodegenerative disease (3 papers, 2021 to 2023). A disorder of the central nervous system characterized by gradual and progressive loss of neural tissue and neurologic function. "It was recently reported that the level of neuroligin-1 (Nlgn1), a post-synaptic cell adhesion protein, was reduced in the CSF of patients with AD (n = 43) compared with controls (n = 42), indicating that Nlgn1 is an interesting synaptic biomarker candidate for neurodegenerative diseases." (PMID 35448530, 2022). "In this study, we addressed in two sets of experiments (Study 1–2) the question whether Nlgn1 protein levels are changed in TBS extracts from various brain regions from patients with neurodegenerative diseases." (PMID 33522967, 2021). "Nlgn1 is a trans-synaptic adhesion molecule important for synapse structure and memory formation, thus its alteration might lead to synaptic dysfunction, and neurodegenerative disease, or it could serve as a marker for such processes." (PMID 33522967, 2021). "In addition, post-synaptic proteins, such as neurogranin and neuroligin-1, and cytoskeletal proteins, such as neurofilament light chain, were also investigated in CSF as markers of synaptic or cytoskeletal dysfunction, occurring in the brains of patients with neurodegenerative diseases." (PMID 35448530, 2022).
adenocarcinoma (2 papers, 2021 to 2022). A common cancer characterized by the presence of malignant glandular cells. "NLGN1 was mainly located in the cytoplasmic membrane of normal glandular cells and adenocarcinoma cells." (PMID 34340665, 2021).
gastrointestinal disorders (1 paper, 2022). "In addition, four genes PDE4D, PKP2, NLGN1 and ALDH1B1 may be candidate genes for congenital heart defects or gastrointestinal disorders in OSH." (PMID 36302822, 2022).
NLGN1 also shares sentences with these, for which no sentence is quoted: bipolar disorder (3 papers); Intellectual disability (3); anxiety disorder (2); Asperger syndrome (2); Hirschsprung disease (2); Tourette disorder (2); ZIKV infection (2); ADNP syndrome (1); Alcohol (1); Ataxia (1); Barrett esophagus (1); cardiac arrhythmia (1); cognitive disorder (1); deafness (1); glaucoma (1); heart failure (1); learning disorder (1); mental disorder (1); microcephaly (1); narcolepsy (1); oral squamous cell carcinoma (1); ovarian carcinoma (1); personality disorder (1); stress-related disorder (1); Williams-Beuren syndrome (1).